STIM1 (stromal interaction molecule 1)
Diseases named in the same sentence as STIM1 in open-access papers (continued):
Sharing a sentence is not in itself a finding about the gene and the disease.
cervical carcinoma (continued). "Double knockdown of STIM1 and STIM2 also led to the accumulation of Cyclin E and decrement of CKD2 phosphorylation in cervical cancer SiHa cells." (PMID 26917047, 2016). "It is well documented that both STIM1 and Orai1 are required for function of SOCE and STIM1 was particularly reported to participate in tumor growth and metastasis in cervical cancer." (PMID 24797725, 2014). "A study involving immunostaining of overexpressed STIM1 and STIM2 in human cervical cancer revealed that STIM1 is the main endoplasmic reticulum Ca2+-sensing molecule found in the invasive tumour front, indicating that STIM1 plays a role in both tumour growth and invasion." (PMID 37259313, 2023). "The levels of Orai1, STIM1, and HDAC6 were upregulated in cervical cancer cells." (PMID 36230965, 2022). "For example, in cervical cancer, STIM1 regulates the production of VEGF to control the formation of blood vessels, and the formation of tumor could be impaired by inhibiting STIM1." (PMID 34122115, 2021). "Therefore, by altering the focal adhesion turnover and actomyosin contractility of cancer cells, STIM1-dependent SOCE promotes tumorigenesis and tumor metastasis of cervical cancers." (PMID 35008759, 2021). "STIM1 and Orai1 are overexpressed in tumor tissues when compared with non-cancerous or precancerous tissues in patients with cervical cancers." (PMID 35008759, 2021). "Thus, the microtubule-associated HDAC6 can be a cancer-specific target of malignant phenotypes mediated by STIM1-dependent SOCE, at least for cervical cancers with upregulation of HDAC6 and STIM1." (PMID 35008759, 2021). "This STIM1-induced migration was owing to Ca2+-dependent calpain and PYK2-mediated focal adhesion turnover, and the increase in angiogenesis was owing to STIM1-dependent secretion of VEGF from cervical cancer cells." (PMID 32825277, 2020). "An investigation of 24 patients with cervical cancer found that 71 % of the patients showed increased expression of STIM1 in primary cervical cancer tissues compared with non-cancerous tissues." (PMID 27013185, 2016). "STIM1-dependent SOCE is necessary for the activation of Ca2+-dependent protease calpain and tyrosine kinase Pyk2, which regulate the focal-adhesion dynamics of migratory cervical cancer cells." (PMID 23594099, 2013). "For example, a study in the model of human cervical cancer has suggested that the different regulatory effects on the microtubule-dependent STIM1 trafficking between non-cancerous epithelial and cancerous cells could be the key to target cancer cell-specific mechanisms of SOCE activation." (PMID 35008759, 2021). "It was found that the microtubule-dependent STIM1 translocation and subsequent SOCE activation of cervical cancer cells, but not in non-cancerous epithelial cells, was abrogated upon hyperacetylation of α-tubulin by pharmacological blockade or silencing of HDAC6." (PMID 35008759, 2021). "In cervical cancer cells, but not in noncancerous epithelial cells, hyperacetylation of α-tubulin by pharmacological blockade or silencing of HDAC6 abrogated microtubule-dependent STIM1 translocation and inhibit SOCE activation." (PMID 31252656, 2019). "However, this trend of redundancy between STIM1 and STIM2 expressions was not noted in cervical cancer patients, indicating the role of STIM2 in tumor biology may be tissue- or cell-type specific." (PMID 23594099, 2013).
Stormorken syndrome (35 papers, 2016 to 2026). Stormorken-Sjaastad-Langslet syndrome is characterized by thrombocytopathy, asplenia, miosis, muscle fatigue, migraine, dyslexia, and ichthyosis. "Gain-of-function (GoF) mutations in STIM1 cause a spectrum of clinically overlapping disorders historically classified as Stormorken Syndrome (STK), tubular aggregate myopathy (TAM), and York Platelet Syndrome (YPS)." (PMID 42193934, 2026). "York platelet syndrome is a Ca2+ channelopathy caused by gain-of-function in STIM1 through heterozygous mutations, including c.343A > T and c.910C > T." (PMID 37259313, 2023). "Among the most relevant disorders associated with gain-of-function mutations of STIM1 are Stormorken syndrome, York platelet syndrome (YPS), and tubular aggregate myopathy (TAM)." (PMID 37759684, 2023). "In contrast, Stormoken syndrome and York platelet syndrome, caused by dominant gain-of-function mutations in STIM1 or ORAI, and characterized by constitutive activation of store-operated calcium entry (SOCE), do." (PMID 35749414, 2022). "Of note, patients with Stormorken syndrome caused by a STIM1 mutation have been shown to exhibit hypocalcemia." (PMID 35179826, 2022). "Studies on STIM1-R304W with cells from patients with Stormorken syndrome or model mice carrying STIM1-R304W suggest that excessive SOCE is a cause of multisystemic defects caused by STIM1-R304W." (PMID 34439731, 2021). "STIM1 R304W containing a gain-of-function mutation in its C-terminus has been associated with the Stormorken syndrome." (PMID 33333945, 2020). "The genetically inherited Stormorken syndrome disease has been associated with the STIM1 single point R304W mutant." (PMID 29483506, 2018). "Stormorken syndrome is caused by autosomal dominant mutations in the STIM1 gene, which encodes an endoplasmic reticulum Ca2+ sensor." (PMID 30374325, 2018). "York Platelet Syndrome (YPS) is a calcium channelopathy caused by gain of function in STIM1, a gene which acts as a calcium sensor." (PMID 30159190, 2018). "Stormorken syndrome is associated with the R304W mutation in STIM1, which is a Calcium sensor in the endoplasmic reticulum." (PMID 29483506, 2018). "The clinical spectrum of TAM with mutations in STIM1 varies from asymptomatic to slowly progressive limb weakness or Stormorken syndrome." (PMID 27879676, 2016). "Targeting DHHC21 may be therapeutically beneficial for ALPS and diseases associated with deregulated activation of STIM1, such as tubular aggregate myopathy and Stormorken syndrome." (PMID 41279060, 2025). "In humans, STIM1 loss-of-function and gain-of-function mutants have been associated with serious clinical conditions, including immunodeficiencies, Stormorken syndrome, tubular aggregate myopathy, York platelet syndrome, and general myopathies." (PMID 40857319, 2025). "Interestingly, STIM1-E136X was also identified in Stormorken syndrome patients, who harbor a gain of function mutation in the STIM1 C-terminus." (PMID 39456133, 2024). "This new STIM1 mutation widens the spectrum of STIM1 variants causing Stormorken syndrome." (PMID 37759684, 2023). "This unfolding can also be activated by a naturally occurring gain-of-function mutation in human STIM1, R304W, which causes Stormorken syndrome characterized by multiple defects including platelet dysfunction, thrombocytopenia, anemia, tubular aggregate myopathy, and congenital miosis." (PMID 37903816, 2023). "Gain-of-function (GOF) mutations in STIM1 are responsible for tubular aggregate myopathy and Stormorken syndrome (TAM/STRMK), a clinically overlapping multisystemic disease characterised by muscle weakness, miosis, thrombocytopaenia, hyposplenism, ichthyosis, dyslexia, and short stature." (PMID 35812399, 2022).
Stormorken syndrome (continued). "Stormorken syndrome, which symptoms comprise small stature, bleeding tendency, muscle fatigue, mitosis without ptosis, asplenia, headache, dyslexia, and ichthyosis, is the most severe form of the disease spectrum seen with STIM1 mutations." (PMID 27879676, 2016). "For patients in two families affected by York platelet syndrome, a disorder of then unknown molecular cause, Exomiser prioritized mutations in STIM1." (PMID 26562225, 2016). "Expression of the STIM1-R304W mutant in zebrafish resulted in thrombocytopenia, bleeding, and hypoplastic caudal vein, a phenotype that is reminiscent of the Stormorken syndrome in humans." (PMID 37759684, 2023). "Mutations in STIM1 and ORAI are detected in only a fraction of patients diagnosed TAM/Stormorken syndrome." (PMID 35980353, 2022). "Mouse models for gain-of-function mutations in Stim1 have been generated and found to present with a variable combination of the clinical signs of TAM/Stormorken syndrome in humans." (PMID 35980353, 2022). "In skeletal muscle, the main diseases related to GoF mutations in STIM1 and/or Orai1 are the non-syndromic tubular aggregate myopathy (TAM) and the more complex Stormorken syndrome." (PMID 34685702, 2021). "On the opposite, some gain-of-function mutations in Orai1 or STIM1, allowing a constitutive SOCE or an increased SOCE amplitude are also associated with diseases like the York platelet syndrome or the Stormorken syndrome." (PMID 33371518, 2020). "Note that gain-of-function STIM1 mutations, including TAM and Stormorken syndrome mutations, result in a broad spectrum of multisystem diseases characterized by muscle weakness, thrombocytopenia, hyposplenism, ichthyosis, dyslexia, moisis, and short stature." (PMID 32575830, 2020). "Among the currently known disease-related STIM1 mutants, many of them are linked to severe combined immunodeficiency (SCID), Stormorken syndrome (STRMK), and tubular aggregate myopathy (TAM)." (PMID 33333945, 2020). "Both STIM1 and ORAI1 mutations are linked to three separate, but overlapping, disorders: tubular aggregate myopathy (TAM), Stormorken syndrome and York platelet syndrome." (PMID 31666234, 2019). "Recently, the human gain-of-function (GoF) mutant STIM1 R304W has been discovered in patients suffering of the Stormorken syndrome, which includes the symptoms thrombocytopenia, muscle fatigue, asplenia, miosis, migraine, dyslexia, and ichthyosis." (PMID 29483506, 2018). "The Stormorken syndrome has been described in 1985; however, its correlation to STIM1 R304W is only reported very recently." (PMID 29483506, 2018). "Here we present a dual mechanism by which STIM1 R304W attains the pathophysiological, constitutive activity eliciting the Stormorken syndrome." (PMID 29483506, 2018). "Although the Stormorken syndrome, TAM, and YPS are rear conditions with a well-recognized pathogeny associated with mutations in the N-terminal STIM1 region, certain STIM1 polymorphisms lead to diffuse phenotypes not clearly associated with them that deserve further studies." (PMID 37759684, 2023). "Several studies have shown that some disorders are associated with STIM1 mutations which lead to immune dysregulation, such as non-syndromic tubular aggregate myopathy, York platelet syndrome and Stormorken syndromes." (PMID 34803742, 2021). "In contrast, dominant STIM1 and ORAI1 gain-of-function mutations give rise to tubular aggregate myopathy and Stormorken syndrome (TAM/STRMK), forming a clinical spectrum encompassing muscle weakness, thrombocytopenia, ichthyosis, hyposplenism, short stature, and miosis." (PMID 33250786, 2020). "In contrast, dominant STIM1 and ORAI1 gain-of-function (GoF) mutations inducing excessive Ca2+ entry through SOCE over-activation were found in patients with tubular aggregate myopathy (TAM) and Stormorken syndrome (STRMK)." (PMID 33250786, 2020).
Stormorken syndrome (continued). "Our recent study additionally reveals a slight, destabilizing impact for the CC1α2 domain in STIM1, which is drastically enhanced by the R304W mutation therein, which fully activates STIM1 without store depletion and is associated with the Stormorken syndrome." (PMID 26825122, 2016). "Several dominant GoF mutations in Orai1 and STIM1 have been identified in patients with tubular aggregate myopathy (TAM) and Stormorken syndrome (STRMK)." (PMID 40459545, 2025). "Furthermore, gain-of-function mutations of Orai1 and STIM1 gave rise to tubular aggregate myopathy (TAM) and Stormorken syndrome (STRMK), forming a clinical spectrum encompassing muscle weakness, myalgia, and cramps, and additional multi-systemic signs, including short stature." (PMID 34638799, 2021). "A recent study has reported five novel STIM1 mutations not related to TAM, Stormorken syndrome, or YPS but leading to muscle phenotype in individuals between 26 and 57 years old." (PMID 37759684, 2023).
Immunodeficiency (31 papers, 2012 to 2025). Failure of the immune system to protect the body adequately from infection, due to the absence or insufficiency of some component process or substance. "These defects are reminiscent of the attenuated T cell function reported in other ORAI1- and STIM1-deficient patients and likely contribute to the patient’s severe immunodeficiency." (PMID 41200103, 2025). "STIM1-ORAI1 coupling is required for the proliferation of T cells, and patients bearing loss-of-function mutations in STIM1 or ORAI1 suffer from severe combined immunodeficiencies." (PMID 40116769, 2025). "Loss-of-function or mutation in the STIM1 gene eliminates Ca2+ influx in T cells, leading to patient immunodeficiency." (PMID 38962804, 2024). "This phenotype, which only presents mild immune deficiencies, was caused by a guanine insertion after position 685 in the coding sequence of STIM1, a frameshift that changes phenylalanine 229 to leucine and induces a premature termination codon." (PMID 37759684, 2023). "Loss of STIM1 in cellular models causes spontaneous IFN-I production and mutations in STIM1 are linked to a severe immune deficiency with autoimmune complications." (PMID 34084165, 2021). "Another mutation R429C, which is situated in STIM1 C-terminus, impairs coupling to Orai1 and has been connected to combined immune deficiencies." (PMID 33333945, 2020). "Lack of STIM1 expression has been reported to cause immunodeficiencies including severe bacterial, viral, or fungal infections and thus, repeated episodes of pneumonia, meningitis, or gastroenteritis." (PMID 33333945, 2020). "In contrast, the homozygous inheritance of the R429C mutation in CC3 of STIM1 results in severe immunodeficiency, characterized by impairment of T-cell activation, autoimmune cytopenia, lymphoproliferation and prolonged diarrhea." (PMID 30366379, 2018). "STIM1 deficiency has been reported in ~20 patients; interestingly, almost every patient manifests myopathy as well as immunodeficiency." (PMID 29145451, 2017). "In humans, STIM1 loss-of-function mutations were identified in patients afflicted with an immunodeficiency and autoimmunity syndrome." (PMID 29145451, 2017). "Mutations in human STIM1 and Orai1 have been found in patients with immunodeficiency, highlighting the importance of SOCE in T cell activation." (PMID 28240257, 2017). "Mutations in STIM1 and Orai1 genes are clinically characterized by severe immunodeficiency and congenital myopathy in human patients." (PMID 22984609, 2012). "These phenotypes in immune cells of Stim1- and Orai1-deficient mice are consistent with those of the severe combined immunodeficiency (SCID) symptoms found in human patients who have mutations in the Stim1 or Orai1 gene, resulting in abnormal STIM1 or Orai1 functions." (PMID 30340324, 2018). "Orai1−/− T cells have been shown to proliferate normally despite reduction in function and many human families with immunodeficiency due to mutations in STIM1 show a normal T-cell count, despite the immunologic deficit in the normal functioning of their immune cells." (PMID 24000152, 2013). "They proposed that loss-of-function STIM1 mutations resulted in impairment of Ca2+ influx resulting in defects of gene expression, cell growth and division, and immune dysfunction particularly NK-cell and T-cell inactivation, contributing to severe immunodeficiency." (PMID 34803742, 2021). "It has been reported that STIM1 protein has novel and unexpected physiological and pathophysiological roles in several tissues, the clinical phenotype of STIM1-deficient patients was characterized by immunodeficiency together with autoimmune disease, congenital myopathy and ectodermal dysplasia." (PMID 27863410, 2016). "Loss-of-function variants in STIM1 and ORAI1 cause calcium release-activated channelopathies (CRAC) with ectodermal dysplasia, leading to enamel defects and anhidrosis, immunodeficiency, and muscular hypotonia with muscle weakness." (PMID 39804930, 2025).